TMCO5A (transmembrane and coiled-coil domains 5A)
Synonyms: TMCO5; MGC35118
Tractability: Antibody: UniProt predicts a signal peptide or a membrane-spanning region.
Gene: Protein-coding gene on chromosome 15 (37,921,858 to 37,967,724, forward strand). Ensembl gene ENSG00000166069.
Subcellular location: Endoplasmic reticulum membrane; Nucleus membrane; Cytoplasm, cytoskeleton
Subcellular location (Human Protein Atlas): Cytosol; Plasma membrane
Gene Ontology:
Molecular function: protein binding
Cellular component: plasma membrane; endoplasmic reticulum membrane; manchette; nuclear membrane; cytoskeleton
Genetic constraint (gnomAD): Loss-of-function variants: 32 observed, 37.61 expected, observed/expected ratio (o/e) 0.85, 90% interval 0.64 to 1.14. The upper end of that interval is the gene's LOEUF score, 1.14, which puts it in group 5 of 6, group 1 being the genes least tolerant of losing a copy. Missense variants: 344 observed, 317.59 expected, observed/expected ratio (o/e) 1.08, 90% interval 0.99 to 1.18. Synonymous variants: 126 observed, 111.99 expected, observed/expected ratio (o/e) 1.13, 90% interval 0.97 to 1.3.
Homologues: Orthologues: chimpanzee TMCO5A (95% identical), macaque TMCO5A (95% identical), rabbit TMCO5A (75% identical), pig TMCO5A (75% identical), dog TMCO5A (74% identical), mouse Tmco5 (71% identical), rat Tmco5a (71% identical), guinea pig TMCO5A (66% identical). Paralogues in human: SMCO2 (20% identical), CCDC188 (16% identical).
Diseases named in the same sentence as TMCO5A in open-access papers:
TMCO5A is named in the same sentence as 4 diseases in open-access papers, as found by Europe PMC text mining. Sharing a sentence is not in itself a finding about the gene and the disease. The quoted sentences say what the papers report.
ovarian carcinoma (1 paper, 2019). A malignant neoplasm originating from the surface ovarian epithelium. "Finally we note that hypermethylation of TMCO5A is associated with worse prognosis in ovarian cancer." (PMID 31136571, 2019).
tumor (1 paper, 2024). "On the other hand, variants associated with the PSG5, HLA-DRB5 and TMCO5A genes present an opposite trend, with a higher VAF in the primary tumor and lower in metastases." (PMID 39409151, 2024). "Finally, in the TMCO5A gene, the VAF is 0.6 in the primary tumor, but is reduced to 0.3 in the lung metastasis and 0.4 in the skin metastasis, respectively." (PMID 39409151, 2024).
TMCO5A also shares sentences with these, for which no sentence is quoted: male infertility (2 papers); schizophrenia (1).